UHRF1 (ubiquitin like with PHD and ring finger domains 1)
Diseases named in the same sentence as UHRF1 in open-access papers (continued):
Sharing a sentence is not in itself a finding about the gene and the disease.
Fanconi anemia (2 papers, 2015 to 2023). Fanconi anemia (FA) is a hereditary DNA repair disorder characterized by progressive pancytopenia with bone marrow failure, variable congenital malformations and predisposition to develop hematological or solid tumors. "UHRF1 accumulation at damage sites precedes the recruitment of important effector proteins, such as FANCD2 (Fanconi anemia complementation group D2), which, in turn, is necessary for the recruitment of other factors of the Fanconi anemia (FA) repair pathway." (PMID 37630248, 2023).
ICF syndrome (2 papers, 2020 to 2024). "Hence, we propose that hypomethylation due to inefficient DNMT1/UHRF1 recruitment at pericentromeric repeats by defects in the CDCA7/HELLS complex could induce pericentromeric instability, which may explain a part of the molecular pathogenesis of ICF syndrome." (PMID 33082427, 2020).
influenza pneumonia (2 papers, 2025). "Because the loss of UHRF1-mediated maintenance DNA methylation promoted transcriptional instability in iTregs, we asked whether the loss of UHRF1 limits the ability of adoptively transferred iTregs to promote recovery following influenza pneumonia." (PMID 40956625, 2025). "UHRF1 is a DNA methylation maintenance protein that can promote regulatory T cell-mediated recovery following viral pneumonia, suggesting its potential role in DP-mediated pneumonia recovery." (PMID 41000417, 2025).
kidney cancer (2 papers, 2009 to 2022). Primary or metastatic malignant neoplasm involving the kidney. "In order to explore the immunohistochemical differences between the UHRF1 gene in the three kidney cancer tissues (KICH, KIRC, and KIRP) and normal kidney tissues, we analyzed the IHC results provided by the HPA database." (PMID 35656341, 2022). "The expression of UHRF1 in normal kidney tissue and the three kinds of kidney cancer tissues in the TCGA and GTEx databases is significantly different." (PMID 35656341, 2022). "At the same time, UHRF1 has more significant tumor immunity and DNA methylation effects in kidney cancer types." (PMID 35656341, 2022). "So it is very important to explore the relationship between UHRF1 expression and different molecular level modification in kidney cancer and various tumors." (PMID 35656341, 2022). "We performed real-time TaqMan quantitative reverse transcription–PCR and immunohistochemistry to examine expression levels of UHRF1 in bladder and kidney cancers." (PMID 19491893, 2009). "High expression of UHRF1 in kidney cancer was also observed." (PMID 19491893, 2009). "On the other hand, the UHRF1 gene was negative or moderately stained by IHC in normal kidney tissues and the staining morphology was regular, while in the three types of kidney cancer tissues, it was stained moderately or strongly with disordered tissue morphology." (PMID 35656341, 2022). "Thus, detection of UHRF1 mRNA overexpression in surgical specimen might be useful as a prognosis tool in kidney cancer, but immunohistochemical staining of UHRF1 in the cancer may not be useful." (PMID 19491893, 2009).
kidney tumors (2 papers, 2009 to 2017). "By investigating mRNA levels, UHRF1 overexpression was found to be associated with several characteristics of kidney tumor patients, including 5-year survival rates, pathological staging and histological grade." (PMID 28881702, 2017). "In contrast, expression of UHRF1 in kidney tumours was significantly increased compared with in normal kidney and in oncocytomas (P<0.0001 and 0.0206, respectively)." (PMID 19491893, 2009). "Expression levels of UHRF1 in six oncocytomas (benign neoplasm in kidney), 71 kidney tumours, and 124 bladder tumours including 11 upper tract TCCs from UK patients were examined by TaqMan real-time qRT—PCR." (PMID 19491893, 2009). "Next, we compared UHRF1 expression in bladder tumours with that in 12 normal tissues, 21 normal kidneys, 6 oncocytomas, and 72 kidney tumours." (PMID 19491893, 2009). "Thus, we examined expression of UHRF1 in urinary system cancers collected in the United Kingdom and found that UHRF1 was moderately upregulated in the kidney tumours and significantly overexpressed in bladder tumours, especially in the upper tract TCCs at the mRNA level." (PMID 19491893, 2009). "However, the levels of upregulation of UHRF1 in bladder tumours were much higher than that in kidney tumours (P<0.0001), suggesting that UHRF1 might be a sensitive tool for detection of bladder tumours, especially the upper tract TCCs, which are currently often found in advanced stages." (PMID 19491893, 2009). "Whereas, we did not detect significant overexpression of UHRF1 in kidney tumours at the protein level, although the high expression of UHRF1 in kidney tumours at the mRNA level correlated with poor survival rate, advanced pathological staging, and increasing histological grade." (PMID 19491893, 2009).
male infertility (2 papers, 2019 to 2020). The inability of the male to effect fertilization of an ovum after a specified period of unprotected intercourse. "Since ablation of UHRF1 in postnatal germ cells caused spermatogenesis failure and male infertility, we next asked when and how germ cells are lost upon deletion of UHRF1 in postnatal testes." (PMID 31624244, 2019). "UHRF1 deficiency led to failure of meiosis and male infertility." (PMID 32081844, 2020).
Obesity (2 papers, 2019 to 2024). Accumulation of substantial excess body fat. "In conclusion, our data show that UHRF1 positively regulates 3T3-L1 adipogenesis and limits fibrosis by suppressing GPNMB and TGF-β signaling cascade, highlighting the potential relevance of UHRF1 and its targets to the clinical management of obesity and linked metabolic disorders." (PMID 38789534, 2024). "Taken together, our results indicated that UHRF1 can promote proliferation of hADSCs and suppress adipogenesis thorough inhibiting PPARγ, and this study may provide a new insight for effective treatment of obesity and related metabolic diseases." (PMID 31428652, 2019). "This study is the first to report that UHRF1 modulates adipogenesis through GPNMB and TGF-β activation, and it highlights the significance of studying UHRF1 and its targets as a potential therapeutic approach to obesity preventive healthcare." (PMID 38789534, 2024).
pancreatic adenocarcinoma (2 papers, 2016 to 2017). "For instance, power blot assay identified UHRF1 among differentially expressed proteins in pancreatic adenocarcinoma, which is extremely aggressive and difficult to diagnose with survival rate of less than 5% in five years." (PMID 28881702, 2017). "UHRF1 has been shown to act effectively as a marker to distinguish pancreatic adenocarcinoma, chronic pancreatitis, and normal pancreas tissue." (PMID 26884069, 2016). "Moreover, UHRF1 was selectively overexpressed in pancreatic adenocarcinoma tissues while it was not detectable in normal pancreatic tissue or chronic pancreatitis specimens." (PMID 28881702, 2017).
papillary thyroid cancer (2 papers, 2018 to 2022). "Here we found that UHRF1 was highly expressed in human ATC compared with normal tissue and papillary thyroid cancer (PTC)." (PMID 30174788, 2018).
renal carcinoma (2 papers, 2017 to 2022). A carcinoma arising from the epithelium of the renal parenchyma or the renal pelvis. "In the results of this study, UHRF1 levels are associated with the degree of immune invasion of renal cancer type." (PMID 35656341, 2022). "The aim of our study was to explore the characterization of UHRF1 in generalized cancer and its potential function in renal cancer (KIRP, KIRC, and KICH)." (PMID 35656341, 2022). "We analyzed the correlation between the expression level of UHRF1 gene and the prognosis of patients with different stages of renal cancer by drawing a Sankey map and carried out data visualization." (PMID 35656341, 2022). "By further understanding its functional scope, we can make UHRF1 an effective biomarker for the diagnosis and treatment of renal cancer." (PMID 35656341, 2022). "In conclusion, this study demonstrates that UHRF1 plays a key role in renal cancer through DNA methylation and the immune microenvironment." (PMID 35656341, 2022). "Both immune infiltration and DNA methylation were used to evaluate the importance and method of UHRF1 in renal cancer." (PMID 35656341, 2022). "Unfortunately, the functional role of UHRF1 in renal cancer is still not fully understood." (PMID 35656341, 2022). "The high expression level of UHRF1 is related to the survival rate of renal cancer." (PMID 35656341, 2022). "In the prognosis of different stages of renal cancer, the high expression of UHRF1 gene was significantly correlated with the death of patients with renal cancer, while the low expression was significantly correlated with the survival of patients with renal cancer." (PMID 35656341, 2022). "Our results showed that UHRF1 gene expression was correlated with four methyltransferases (DNMT1, DNMT2, DNMT3A, and DNMT3B) in a variety of tumors, and KICH KIRC KIRP was positively correlated with methyltransferase, suggesting that UHRF1 may be an epigenetic driver of renal cancer type." (PMID 35656341, 2022). "Our results showed that UHRF1 inhibited TXNIP expression by enslating HDAC1 to the TXNIP promoter and mediating deacetylation of histone H3K9, thus confirming that UHRF1 may promote tumor progression through epigenetic regulation of TXNIP in renal cancer." (PMID 35656341, 2022). "Similarly, UHRF1 overexpression, in metastatic renal cancer tissues as compared with non-metastatic tissues, correlated with downregulation of non-coding miR-146a-5p, which targets UHRF1 transcription." (PMID 28881702, 2017).
sarcoma (2 papers, 2022 to 2024). A usually aggressive malignant neoplasm of the soft tissue or bone. "In sarcomas, high UHRF1 expression is associated with poorer survival." (PMID 36068209, 2022). "The expression of UHRF1 increases in mesenchymal sarcoma tumors compared to non-sarcomas, promoting cell invasion and correlating with recurrence and overall survival." (PMID 39009887, 2024).
silicosis (2 papers, 2022). Silicosis is a respiratory disease caused by breathing in (inhaling) silica dust. "Immunostaining intensity of UHRF1 was found to be broadly expressed in silicosis patient lungs, especially in the fibrotic area, further implying its vital role in PF." (PMID 36566325, 2022). "Additionally, H&E and IHC staining for UHRF1 reinforced that UHRF1 was highly expressed in patients with silicosis, mainly in the fibrotic area." (PMID 36166308, 2022). "Also, HE and UHRF1 IHC staining were performed in the collected silicosis patient lung samples." (PMID 36566325, 2022).
T-cell ALL (2 papers, 2024 to 2025). "To note, UHRF1 has been identified as a hub gene in chronic myeloid leukemia (upregulated in murine models), and has been reported as a promoter of oncogenesis in T-cell ALL." (PMID 41226303, 2025).
viral pneumonia (2 papers, 2025). Inflammation of the lung parenchyma that is caused by a viral infection. "UHRF1-deficient iTregs display transcriptional instability and poor engraftment after adoptive transfer into mice with viral pneumonia." (PMID 40956625, 2025). "Collectively, adoptive transfer of UHRF1-deficient iTregs compromised recovery from viral pneumonia, and recipients of Uhrf1fl/fl iTregs displayed evidence of a greater degree of peak injury." (PMID 40956625, 2025). "UHRF1-deficient iTregs fail to promote recovery following viral pneumonia." (PMID 40956625, 2025). "In summary, UHRF1-mediated maintenance DNA methylation stabilizes iTreg cellular identity and reparative function following viral pneumonia." (PMID 40956625, 2025). "Adoptive transfer of UHRF1-deficient iTregs results in delayed repair of lung injury following viral pneumonia compared with UHRF1-sufficient iTregs." (PMID 40956625, 2025). "We further demonstrated that maintenance DNA methylation mediated by the epigenetic regulator UHRF1 is necessary for iTreg reparative function during viral pneumonia." (PMID 40956625, 2025). "Here, we tested whether iTregs promote recovery following viral pneumonia and whether iTregs require UHRF1 for their pro-recovery function." (PMID 40956625, 2025).
AIDS (1 paper, 2021). A syndrome resulting from the acquired deficiency of cellular immunity caused by the human immunodeficiency virus (HIV). "In summary, our findings revealed that UHRF1 is an important mediator of HIV-1 latency by controlling Tat-mediated transcriptional activation, providing novel insights on host-pathogen interaction for modulating HIV-1 latency, beneficial for the development of anti-AIDS therapies." (PMID 34465029, 2021).
asthma (1 paper, 2020). "MiR-146-5p targets inflammatory mediators like COX2, IL-1β, KIT, NFKB1, TLR4, TRAF6, and UHRF1 and has been proposed as a predictor for asthma exacerbations in childhood asthma." (PMID 32998415, 2020).
atherosclerosis (1 paper, 2022). A disease characterized by the build-up of fatty material and calcium deposition in the arterial wall resulting in partial or complete occlusion of the arterial lumen. "Genetic alterations in MBD2 and UHRF1 have been linked to various cardiovascular pathologies such as atherosclerosis or arterial aneurism, which can trigger HF." (PMID 35453616, 2022).
B-cell acute lymphoblastic leukemia (1 paper, 2025). A neoplasm of lymphoblasts committed to the B-cell lineage, typically composed of small to medium-sized blast cells. "In this investigation, utilizing single-cell transcriptome sequencing technology, we discerned a correlation between Ubiquitin-like containing PHD and RING finger domain 1 (UHRF1) and the progression of B-cell acute lymphoblastic leukemia." (PMID 40301374, 2025). "Our findings reveal a significant upregulation of UHRF1 in cases of relapsed and refractory B-cell acute lymphoblastic leukemia, thereby serving as a prognostic indicator for poor outcomes." (PMID 40301374, 2025).
biliary tract cancer (1 paper, 2025). "Additionally, one report indicated that miR-124 suppresses UHRF1 expression in intrahepatic CCA, a type of biliary tract cancer." (PMID 41373864, 2025).
bladder tumours (1 paper, 2009). "Here, we report that the overexpression of UHRF1 in bladder tumour is associated with malignant potential of the cancers as defined by the stage and grade." (PMID 19491893, 2009). "Expression levels of UHRF1 in superficial bladder tumours (pTa and pT1) and invasive bladder tumours (pT2–pT4) were both significantly higher than those in normal bladders by Mann–Whitney's U-test (P=0.0063 and 0.0034, respectively)." (PMID 19491893, 2009). "We verified the overexpression of UHRF1 in bladder tumour tissues at the protein level by immunohistochemistry." (PMID 19491893, 2009). "Overexpression of UHRF1 in bladder tumours was confirmed at the protein level by immunohistochemistry." (PMID 19491893, 2009). "Overexpression of UHRF1 was further confirmed in bladder tumours from 36 Japanese patients by microarray analysis." (PMID 19491893, 2009). "Expression of UHRF1 in these bladder tumours was compared with the corresponding adjacent normal tissues from the same patients, and tumour/normal ratio was obtained." (PMID 19491893, 2009). "Expression of UHRF1 was detectable even in bladder tumours at non-advanced stages (grades I and II, pTa/pT1N0M0), although stronger UHRF1 staining was detected in bladder tumours of more advanced stages (pT2–pT4), and grades (grades II and III)." (PMID 19491893, 2009).
clear cell renal cell carcinoma (1 paper, 2021).
colorectal tumors (1 paper, 2021). "Genomic DNA was prepared from AOM/DSS-untreated colorectal tissues and AOM/DSS-induced colorectal tumors that were microdissected from both wild-type and Uhrf1-TTD-KI mice, and the levels of 5mC were quantitatively measured by HPLC." (PMID 33947834, 2021). "The average number of small intestinal and colorectal tumors in Uhrf1+/+/ApcMin/+ is 44.04 and this is reduced to 8.6 in Uhrf1ki/ki/ApcMin/+ mice." (PMID 33947834, 2021).
embryonic carcinoma (1 paper, 2016). "We designed and validated the efficacy and specificity of two small interfering RNAs (siRNAs) against each of the mouse Uhrf1 and Uhrf2 using mouse P19 embryonic carcinoma cells." (PMID 27462454, 2016).
erythroleukemia (1 paper, 2015). Acute erythroid leukemia characterised by the presence of at least 50% erythroid precursors and at least 20% myeloblasts in the bone marrow. "Furthermore, using erythroleukemia type K562, downregulation of UHRF1 transfected with two different shG9a RNAs was further confirmed by real-time PCR and western blot analysis." (PMID 25765655, 2015).
Ewing sarcoma (1 paper, 2024). A small round cell tumor that lacks morphologic, immunohistochemical, and electron microscopic evidence of neuroectodermal differentiation. "Its relevance extends to mesenchymal tumors, such as rhabdomyosarcoma (RMS) and Ewing sarcoma, where DiPRO1 acts as a repressor via the epigenetic regulators TIF1B and UHRF1, maintaining methylation of cis-regulatory elements and gene promoters." (PMID 39009887, 2024).
Hearing impairment (1 paper, 2023). A decreased magnitude of the sensory perception of sound. "In view of this, whether the changes in UHRF1 expression affect the progress of hearing impairment still needs to be further expounded." (PMID 36865496, 2023).
histiocytic lymphoma (1 paper, 2023). "In addition, to find out whether knockdown of UHRF1 or DNMT1 also enhances differentiation in other cell line, we used another blood cancer cell line U-937, which is obtained from histiocytic lymphoma." (PMID 37573395, 2023).
HIV-1 infection (1 paper, 2021). The type species of lentivirus and the etiologic agent of acquired immunodeficiency syndrome (AIDS). "Taken together, these results suggest that UHRF1 inhibits HIV-1 replication and may be an HIV-1 restriction factor for HIV-1 infection and replication." (PMID 34465029, 2021).
hyperlipidaemia (1 paper, 2019). "In addition, EHM inhibited hyperlipidaemia by restoring the expression of genes and proteins related to DNA repair and energy metabolism, and proteins such as Hdac2, Xrcc2, Xrcc3, Uhrf1, and Prkar2b were identified as molecular targets playing key roles in ameliorating hyperlipidaemia." (PMID 31545933, 2019).
influenza (1 paper, 2025). An acute viral infection of the respiratory tract, occurring in isolated cases, in epidemics, or in pandemics; it is caused by serologically different strains of viruses (influenzaviruses) designated A, B, and C, has a 3-day incubation period, and usually lasts for 3 to 10 days. "Transcriptional and DNA methylation profiling of adoptively transferred UHRF1-deficient iTregs that had trafficked to influenza-injured lungs demonstrated transcriptional instability with gain of transcription factors that define effector T cell lineage." (PMID 40956625, 2025). "To further elucidate whether engraftment was influenced by the inflammatory microenvironment of the lung, we harvested adoptively transferred Foxp3-GFP+tdTomato+ cells from the spleens and lungs of Foxp3GFP-DTR recipients of Uhrf1+/+ or Uhrf1fl/fl iTregs that received DTx but not influenza." (PMID 40956625, 2025).
intestinal tumor (1 paper, 2021). "Nevertheless, by using chemical-induced and ApcMin/+ intestinal tumor models, we demonstrated that the moderate DNA hypomethylation caused by Uhrf1-TTD mutation is sufficient to markedly suppress intestinal tumorigenesis." (PMID 33947834, 2021).
myocardial ischemia (1 paper, 2021). A disorder of cardiac function caused by insufficient blood flow to the muscle tissue of the heart. "The Uhrf1 level in the non-infarcted areas was significantly lower than the infarcted areas at 2, 6 and 12 hours after myocardial ischemia-reperfusion in vivo." (PMID 33744855, 2021).